Y_RNA (Y RNA )
Gene: Miscellaneous RNA gene on chromosome 2 (201,808,681 to 201,808,782, forward strand). Ensembl gene ENSG00000202137.
Homologues: Orthologues: chimpanzee Y_RNA (98% identical), macaque Y_RNA (92% identical), pig Y_RNA (77% identical). Paralogues in human: RNY3 (91% identical), Y_RNA (91% identical), RNY3P1 (90% identical), Y_RNA (90% identical), Y_RNA (89% identical), Y_RNA (88% identical), Y_RNA (87% identical), RNY3P11 (86% identical), RNY3P16 (86% identical), Y_RNA (86% identical), RNY3P14 (85% identical), Y_RNA (85% identical), and 97 more.